RNU6-294P (RNA, U6 small nuclear 294, pseudogene)
Gene: Small nuclear RNA gene on chromosome 5 (64,573,569 to 64,573,670, forward strand). Ensembl gene ENSG00000201869.
Homologues: Orthologues: chimpanzee U6 (99% identical), macaque U6 (91% identical), guinea pig U6 (83% identical), dog U6 (80% identical), rabbit U6 (79% identical). Paralogues in human: RNU6-672P (84% identical), RNU6-1060P (83% identical), RNU6-116P (83% identical), RNU6-1249P (83% identical), RNU6-196P (83% identical), RNU6-199P (83% identical), RNU6-378P (83% identical), RNU6-41P (83% identical), RNU6-44P (83% identical), RNU6-748P (83% identical), RNU6-1075P (82% identical), RNU6-1078P (82% identical), and 1286 more.